PYGO2 (pygopus family PHD finger 2)
Diseases named in the same sentence as PYGO2 in open-access papers (continued):
Sharing a sentence is not in itself a finding about the gene and the disease.
adenoma (1 paper, 2016). A neoplasm arising from the epithelium. "Loss of PYGO2 expression in the adenoma was confirmed by immunohistochemistry in Pygo2 deficient animals." (PMID 27811361, 2016). "In summary, we provide in vivo evidence that Pygo2 loss cannot compensate the intestinal hyperproliferation and adenoma formation resulting from Apc truncation." (PMID 27811361, 2016). "Overall, Bcl9-2 upregulation in adenoma of heterozygous Apc mice and chemically induced tumors may further drive tumor progression, which cannot be compensated by loss of Pygo2." (PMID 27811361, 2016). "Thus, Pygo2 ablation apparently cannot prevent adenoma formation that is genetically induced by loss of one functional Apc allele in vivo, which also exhibits loss of the second allele due to loss-of-heterozygosity (LOH)." (PMID 27811361, 2016). "PYGO2 was overexpressed in the hyperproliferative regions during early tumorigenesis, but also in adenoma and colon tumors in mice with Pygo2 wild type background." (PMID 27811361, 2016). "In fact, we found upregulation of nuclear ß-catenin and overexpression of Pygo2 in the adenoma." (PMID 27811361, 2016). "We have previously shown that Pygo2, but not Pygo1, is overexpressed in different stages of human colon cancer and in adenoma of APCMin/+ mice." (PMID 27811361, 2016). "Our preliminary results indicated that deletion of Pygo2 exerts different effects in early phases of intestinal tumor development in contrast to APCMin/+ mice, in which the formation of adenoma was not prevented by constitutive ablation of Pygo2 (Schelp and Brembeck, unpublished data)." (PMID 27811361, 2016). "However, deletion of Pygo2 did also not rescue adenoma formation in this Apc LOF model." (PMID 27811361, 2016).
anaplastic astrocytoma (1 paper, 2016). "Up-regulation of Pygo2 was observed in anaplastic astrocytoma (Apa-tis), diffuse astrocytoma (Dfu-tis) and yellow astrocytoma (Yel-tis) when compared with peritumoral tissue (Ptu-tis) and normal brain tissue (NB-tis)." (PMID 26902498, 2016).
colitis (1 paper, 2022). Inflammation of the colon. "Lentiviral transfection was used to regulate Pygo2 expression in Il‐10−/− mice, and the effects on mesenteric adipocyte differentiation, inflammation, and dysfunction during spontaneous colitis, as well as the possible mechanism, were investigated." (PMID 35707871, 2022). "To examine the role of Pygo2 in CD‐like colitis, we used lentivirus to specifically knock down (KD) or overexpress (OE) Pygo2 in Il‐10−/− mice and the intervention effect in MAT and intestinal mucosa was verified by RT‐qPCR." (PMID 35707871, 2022). "The increase in Pygo2 may be related to mesenteric adipocyte poor differentiation and inflammatory features of CD, and Pygo2 inhibition could alleviate CD‐like colitis by improving mesenteric lesions by regulating the Axin2/GSK3β pathway." (PMID 35707871, 2022). "Then, we further analysed the effect of Pygo2 on mesenteric inflammation, which could interact with colitis during the progression of the disease." (PMID 35707871, 2022). "Pygo2 knockdown significantly ameliorated colitis in Il‐10−/− mice." (PMID 35707871, 2022). "Therefore, Pygo2 knockdown in Il‐10−/− mice can promote PPARγ expression and induce the differentiation of adipocytes, while also inhibiting mesenteric fat inflammation, thereby inhibiting colitis." (PMID 35707871, 2022). "Our data indicated that Pygo2 knockdown could alleviate CD‐like colitis in Il‐10−/− mice." (PMID 35707871, 2022). "The most important finding in the study was that Pygo2 was increased in CD‐MAT and participated in adipocyte differentiation following colitis." (PMID 35707871, 2022). "The absence of Pygo2 attenuated mesenteric inflammation and adipocyte differentiation, which eventually ameliorated the clinical signs of colitis in Il‐10−/− mice." (PMID 35707871, 2022). "In the present study, we aimed to measure the level of Pygo2 in CD MAT and to investigate whether Pygo2 influences the disease course of experimental colitis." (PMID 35707871, 2022). "Inhibiting of Pygo2 attenuated the development of MAT lesions in Il‐10−/−mice by promoting the differentiation of adipocytes, reducing inflammation, and leading to the amelioration of colitis partly through the Axin2/GSK3β pathway." (PMID 35707871, 2022). "The absence of Pygo2 attenuated the development of MAT lesions in Il‐10−/− mice by promoting the differentiation of adipocytes, leading to the amelioration of colitis partly through the Axin2/GSK3β pathway." (PMID 35707871, 2022).
colon adenocarcinoma (1 paper, 2024). "Pygopus family PHD finger 2(PYGO2), a crucial co-activator of the Wnt/β-catenin transcriptional complex, has been detected in multiple tumors, including colon adenocarcinoma (COAD), epithelial ovarian, renal cell carcinoma, and breast cancers." (PMID 40034933, 2024).
colon cancer (1 paper, 2016). "In fact, Pyrvinium pamoate, an anti-helminth drug, was shown to decrease PYGO2 protein levels in colon cancer cells lines with Apc and Ctnnb1 mutations, and in ApcMin/+ mice." (PMID 27811361, 2016). "Of note, a subgroup of colon tumors derived from Pygo2 deficient animals showed significant repression of Axin2, suggesting that Wnt/ß-catenin signaling is partially inhibited in these tumors of Pygo2 deficient mice." (PMID 27811361, 2016). "Taken together, ablation of Pygo2 can partially rescue the tumor formation of chemically induced colon tumors that may be linked to hyperactivated Wnt/ß-catenin signaling." (PMID 27811361, 2016). "Thus, loss of Pygo2 cannot prevent colon tumor development in the chemically induced carcinogenesis model, but may delay tumor progression in terms of tumor number and size." (PMID 27811361, 2016). "On the other hand, several studies revealed a specific role in particular for Pygo2 and Bcl9-2 in diseases such as colon cancer to hyperactivate canonical Wnt signaling." (PMID 27811361, 2016). "In the present study, we have analyzed the in vivo role of Pygo2 using chemically induced colon cancer and conditional Apc LOF and Ctnnb1 GOF mouse models." (PMID 27811361, 2016). "Colon tumors from controls and Pygo2 knockout animals showed partially invasiveness into the submucosa and high proliferation as detected by BrdU stains." (PMID 27811361, 2016). "Intriguingly, we found that Pygo2 deletion delayed chemically induced colon tumor formation and totally suppressed intestinal hyperproliferation induced by stabilized ß-catenin." (PMID 27811361, 2016). "Despite PYGO2 overexpression in colon cancer, our preliminary studies revealed that the knockout of Pygo2 in the intestine had no influence on embryonic intestinal development and for adult intestinal homeostasis (Schelp and Brembeck, unpublished data)." (PMID 27811361, 2016). "The total number of colon tumors was highly significantly reduced in Pygo2 mutant animals (mean number of tumors 2.5 in Pygo2 knockouts versus 4.2 in controls, P = 0.0023)." (PMID 27811361, 2016). "Previous studies showed that Pygo2 is upregulated in murine intestinal tumors and human colon cancer, but is apparently dispensable for normal intestinal homeostasis." (PMID 27811361, 2016). "The most important finding for the role of Pygo2 in our study was the regulation of c-Myc as an essential transcription factor for colon cancer." (PMID 27811361, 2016). "We describe that Pygo2 knockout reduced tumor formation in chemically induced colon tumors." (PMID 27811361, 2016). "It is therefore possible that Pygo2 loss and the effects on Wnt signaling are not sufficient to completely suppress colon tumor formation in this animal model." (PMID 27811361, 2016). "Indeed, our previous studies demonstrated significant overexpression of PYGO2 in tumors of APCMin/+ mice, colon cancer cells and in human colon cancer, indicating a possible role in tumor development." (PMID 27811361, 2016). "However, our data indicate that Pygo2 deletion delays tumor growth by inhibition of Wnt signaling in chemically induced colon tumors." (PMID 27811361, 2016). "Besides colon cancer, Pygo2 was also suggested to have a potential role in various other malignancies including breast, ovarian, lung, glioblastomas and liver cancers." (PMID 27811361, 2016). "Therefore, the present study was designed to investigate the role of Pygo2 during colon cancer initiation and progression in vivo." (PMID 27811361, 2016). "In addition, Pygo2 knockdown in colon cancer cells is able to suppress Wnt target gene transcription." (PMID 27811361, 2016). "Thus, targeting Pygo2 may represent an attractive therapeutic option to suppress or arrest tumor growth in human colon cancer in a context dependent manner." (PMID 27811361, 2016). "Pygo2 failed to suppress Sox9 overexpression in Apc LOF, and only partially reduced elevated Sox9 in colon tumors and Ctnnb1 GOF mice." (PMID 27811361, 2016).
infertile (1 paper, 2022). "The obtained P values comparing MAF between case and control groups showed a significant difference between MAF of infertile patients and controls in the case of PYGO2 rs141722381 (P value = .007), but there was no such a difference between case and control groups in the other studied SNPs." (PMID 36197138, 2022).
intestinal cancer (1 paper, 2016). "This may indicate that the tumor promoting function of Pygo2 in the Ctnnb1 GOF model may be partly regulated by the induction of Lgr5-positive stem-like cells that are known to be the origin of intestinal cancer." (PMID 27811361, 2016).
intestinal tumors (1 paper, 2016). "Next, we characterized the in vivo role of Pygo2 for the transcriptional activation of Wnt/ß-catenin target genes and of genes that are implicated in intestinal tumor initiation and progression." (PMID 27811361, 2016). "First we compared the effects of Pygo2 loss during the acute phase of intestinal tumor initiation induced by homozygous truncated Apc (Apc LOF; Pygo2+/+, +/− and −/−) and by heterozygous stabilized ß-catenin (Ctnnb1 GOF; Pygo2+/+, +/− and −/−)." (PMID 27811361, 2016). "Our results presented here indicate that Pygo2 synergizes intestinal tumor formation in vivo that is primarily driven by aberrant Wnt signaling." (PMID 27811361, 2016). "To test the potential pro-oncogenic role of Pygo2 in intestinal tumors, we first challenged constitutive, intestine specific Pygo2 deficient mice (“Pygo2−/−”; corresponding to the genotype VilCre; Pygo2 Δ/Δ) and control littermates (Pygo2lox(ex3)/lox(ex3))." (PMID 27811361, 2016). "In contrast, Pygo2, similar to Bcl9/Bcl9-2, may drive intestinal tumor formation by increasing aberrant Wnt signaling in vivo." (PMID 27811361, 2016). "Finally, we analyzed if these target genes were also affected in chemically induced intestinal tumors following Pygo2 knockout." (PMID 27811361, 2016). "Thus, also chemically induced intestinal tumors show a similar pattern of gene regulation in the context of Pygo2 knockout as seen in early stages of tumorigenesis induced by Apc LOF or Ctnnb1 GOF." (PMID 27811361, 2016).
liver cancer (1 paper, 2015). An epithelial or non-epithelial malignant neoplasm that arises from the liver. "Base on our experiment finding on HCC cell lines that down-regulated of Pygo2 can increase E-cadherin expression, we wonder if their relationship hold true in hepatic cancer tissues." (PMID 25871475, 2015).
lobular carcinomas (1 paper, 2021). "Therefore, although pathway analysis connected BCL9 and PYGO2 protein to the “beta-catenin:TCF transactivating complex,” it is possible that those proteins play a special role in beta-catenin-independent signaling pathway both in ductal and lobular carcinomas." (PMID 33808143, 2021).
melanoma (1 paper, 2021). A malignant, usually aggressive tumor composed of atypical, neoplastic melanocytes. "Of the other six significant genes identified in the screen (TRIM28, CDYL2, DMAP1, CBX5, PYGO2), TRIM28 is known to increase melanoma tumor propagation potential." (PMID 33527896, 2021).
Obesity (1 paper, 2022). Accumulation of substantial excess body fat. "A recent meaningful study found that Pygo2 can inhibit adipocyte differentiation in a high‐fat feeding‐induced mouse obesity model." (PMID 35707871, 2022).
tumor (34 papers, 2010 to 2025). "EphrinA4: Pygopus-2 (Pygo2) expression is significantly higher in cancerous tissues and is associated with age, tumor size, metastasis, vascular invasion, and tumor differentiation." (PMID 37444544, 2023). "The effect on tumor formation by Pygo2 knockout was linked to the repression of specific deregulated Wnt target genes, in particular of c-Myc." (PMID 27811361, 2016). "Remarkably, the number and size of chemically induced tumors was significantly reduced in Pygo2 deficient mice, suggesting that Pygo2 has a tumor promoting function." (PMID 27811361, 2016). "The different members of the Lef/Tcf transcription factor family have been implicated in tumorigenesis, and we found strong upregulation of Tcf1 and Lef1 in the tumor models, which were only in part downregulated by Pygo2 loss." (PMID 27811361, 2016). "Abnormal Pygo2 expression was associated with poor differentiation and a high Tumor (T), Node (N) and Metastases (M) stage in NSCLC patients, and correlated with poor prognosis." (PMID 23865714, 2013). "Prognostic Implications: The absence of PYGO2 could serve as a prognostic marker, suggesting that the tumor may be more aggressive or resistant to certain treatments, depending on how the loss of PYGO2 impacts the cell’s characteristics." (PMID 41133538, 2025). "Tumor Suppression Loss: PYGO2 mutations that lead to the loss of function may impair tumor suppressor pathways, making cells resistant to apoptosis and increasing their proliferative potential." (PMID 41133538, 2025). "Interestingly, it has been shown that PYGO2 mRNA expression has a significant association with tumor grade and size in ESCC." (PMID 40034933, 2024). "A significant association between PYGO2 protein expression and tumor invasion was found." (PMID 40034933, 2024). "Moreover, the role of Pygo2 appears to be associated with the signaling output of deregulated Wnt signaling in the different tumor models." (PMID 27811361, 2016). "In addition, abnormal expression of Pygo2 in cancers not only associated with tumor growth and apoptosis, but also has an important clinic-pathological significance." (PMID 25871475, 2015). "Abnormal Pygo2 expression in tumor cells has been implicated in tumor progression." (PMID 23865714, 2013). "Thus, targeting Pygo2 in malignant tumors that harbor Ctnnb1 mutations may result in suppression of tumor formation and growth." (PMID 27811361, 2016). "Further analysis revealed that Pygo2+ CD8+ T cells primarily engage with tumor cells and macrophages through immune checkpoint receptor-ligand pairs, such as CD74, CD55, and SPP1." (PMID 40771810, 2025). "The findings indicate a significant upregulation of Pygo2 expression in GC tissues, particularly within tumor cells and T cells." (PMID 40771810, 2025). "The results showed that Pygo2+ CD8+ T cells exhibited significantly stronger interactions with tumor cells and macrophages compared to Pygo2- CD8+ T cells." (PMID 40771810, 2025). "In TNBC, SNHG22 drives tumor progression by sponging miR-324-3p and upregulating SUDS382; LRRC75A-AS1 (SNHG29) promotes tumor progression by targeting the miR-380-3p/BAALC pathway, and SNHG8 promotes tumor progression through the miR-335-5p/PYGO2 axis." (PMID 41301542, 2025). "In the present case, characterized by a rare HCC profile with PIK3CA positivity and PYGO2 negativity, the molecular profile suggests an aggressive tumor phenotype driven by activation of the PI3K signaling axis." (PMID 41133538, 2025). "Previous research regarding the role of Pygo2 in tumor prognosis has predominantly concentrated on the analysis of tumor tissues or cellular models." (PMID 40771810, 2025). "The findings revealed that the expression of Pygo2 was markedly elevated in GC tissue, with heightened expression predominantly observed in tumor cells and CD8+ T cells." (PMID 40771810, 2025). "Meanwhile, flow cytometry was used to analyze the expression of Pygo2 in T cells in fresh tumor tissues of GC patients." (PMID 40771810, 2025).